MYD88 (MYD88 innate immune signal transduction adaptor)
Diseases named in the same sentence as MYD88 in open-access papers (continued):
Sharing a sentence is not in itself a finding about the gene and the disease.
Waldenström macroglobulinemia (56 papers, 2013 to 2025). "The MYD88 gene mutation in IgM monoclonal gammopathy of undetermined significance (MGUS) correlates with a 20-fold heightened chance of developing Waldenström’s macroglobulinemia." (PMID 39859314, 2025). "Over 90% of individuals with Waldenström’s macroglobulinemia exhibit the p.L265P gain-of-function mutation in the MYD88 gene." (PMID 39859314, 2025). "BTK inhibitors are well recognized for their effectiveness in treating Waldenstrom macroglobulinemia with MyD88 mutation." (PMID 38765016, 2024). "Approximately 93–97% of patients with Waldenstrom macroglobulinemia have a somatic mutation in MyD88, which triggers tumor growth by activating NF-κB signaling via BTK." (PMID 38765016, 2024). "Bone marrow biopsy showed lymphoplasmacytic lymphoma (LPL) and tested positive for the MYD88 L265P mutation suggesting Waldenström macroglobulinemia (WM)." (PMID 36401435, 2022). "We report a case of mu heavy chain disease with MYD88 L265P mutation and deletion of 6q, genetic aberrations that are both strongly associated with lymphoplasmacytic lymphoma/Waldenström macroglobulinemia." (PMID 35932039, 2022). "Allele-specific polymerase chain reaction for detecting MYD88 L265P mutations is more sensitive for confirming lymphoplasmacytic lymphoma/Waldenstrom’s macroglobulinemia in pleural fluid." (PMID 32654665, 2020). "Our case of a patient with untreated lymphoplasmacytic lymphoma/Waldenstrom’s macroglobulinemia with extramedullary pleural effusion is the first documented case of pleural fluid MYD88 L265P mutation status in a community hospital setting." (PMID 32654665, 2020). "The simultaneous presentation of Waldenström's macroglobulinemia and MYD88 mutation with multiple myeloma in the same patient is very rare and only a few cases have been reported in the literature." (PMID 30868035, 2019). "The MYD88 mutation has a prevalence in Waldenström macroglobulinemia of anywhere from 87 to 100%12." (PMID 29712895, 2018). "The MYD88 L265P somatic variant (MYD88) has a high prevalence in Waldenstrom's Macroglobulinemia (WM), a form of lymphoplasmacytic lymphoma (LPL) associated with monoclonal IgM." (PMID 28286680, 2017). "The circulating MYD88 c.T778C mutation has been described in patients suffering from Waldenström macroglobulinemia (WM) or IgM monoclonal gammopathy of undetermined significance (MGUS)." (PMID 28636991, 2017). "The MYD88 L265P is a recurrent somatic mutation in neoplastic cells from patients with Waldenström Macroglobulinemia (WM)." (PMID 26352266, 2015). "Since L265P mutation of MYD88 gene was prevalent in IgM-secreting Waldenström macroglobulinemia, and it was reported in up to 29% of DLBCL with an ABC-type, we expected to find this mutation in the IgM-secreting DLBCL subset." (PMID 24705344, 2014). "L265P mutation in the MYD88 gene has recently been reported in Waldenström’s macroglobulinemia; however the incidence has been different according to the methods used." (PMID 24224040, 2013). "Waldenström macroglobulinaemia (WM) is a rare lymphoplasmacytic disease that is hallmarked by B‐cell infiltration of the bone marrow, an overexpression of IgM class antibodies and an activating mutation of MYD88 (L265P)." (PMID 41447345, 2025). "Recently, KIN-8194, a dual inhibitor of BTK (IC50 = 0.915 nM) and HCK (IC50 < 0.495 nM), was shown to potently affect the survival of ABC-type DLBCL and Waldenström Macroglobulinemia with a pathogenic Myd88-L265P mutation, while minimally affecting healthy B-cells." (PMID 38454120, 2024). "Remarkably, MYD88 mutations are present in ~70% of primary testis lymphomas (PTLs), primary central nervous system lymphomas (PCNSLs) and primary vitreoretinal lymphomas (PVRLs) and in over 90% of Waldenström macroglobulinemia (WM) cases." (PMID 37591861, 2023).
Waldenström macroglobulinemia (continued). "Allele-specific polymerase chain reaction is a sensitive assay for detecting MYD88 L265P mutations in pleural fluid to support the diagnosis of malignant pleural effusion in the setting of Waldenstrom’s macroglobulinemia and helps guide the treatment decision to use ibrutinib." (PMID 32654665, 2020). "Finally, the diagnosis of lymphoplasmacytic lymphoma/Waldenström macroglobulinemia seems unlikely, as an MYD88 mutation was found in only 2/8 patients, and the classical p.L265P mutation was never observed." (PMID 31590326, 2019). "Finally, we report that the MyD88 gain-of-function L265P mutation, frequently encountered in B-cell lymphomas such as Waldenström’s macroglobulinemia, enhances hepcidin expression and iron accumulation in B cell lines." (PMID 30234111, 2018). "It will be interesting to test whether pharmacological inhibitors of this pathway show efficacy in primary tumor cells derived from hematologic malignancies such as Waldenstrom's Macroglobulinemia, where the majority of the cells carry the MYD88[L265P] mutation." (PMID 27303665, 2016). "MYD88 L265P is an established diagnostic marker for LPL, detected in >90% of cases and directly linked to Waldenström’s macroglobulinemia." (PMID 40150070, 2025). "MYD88 L265P is an early mutation in IgM monoclonal gammopathy of undetermined significance (MGUS) and asymptomatic Waldenström macroglobulinemia (WM)." (PMID 40666506, 2025). "Despite recurrent and activating mutations, including MYD88, CXCR4, ARID1A, KMT2D, and CD79B were identified, the genetic basis for Waldenström's Macroglobulinemia (WM) and the risk of progression of IgM MGUS to WM remain to be fully elucidated." (PMID 39711167, 2024). "In ABC-DLBCL and Waldenström macroglobulinemia, ibrutinib is highly effective due to the activation of BTK via mutations in CD79B or the myeloid differentiation primary response gene 88 (MyD88), but in mantle cell lymphoma, these mutations are rare." (PMID 29907126, 2018). "Since 2016, testing for MyD88 was added to the essential recommendations for initial work-up of lymphoplasmacytic lymphoma/Waldenstrom’s macroglobulinemia (LPL/WM) in the National Comprehensive Cancer Network (NCCN) Guidelines." (PMID 30583727, 2018). "Massively parallel sequencing analyses have revealed a common mutation within the MYD88 gene (MYD88L265P) occurring at high frequencies in many non-Hodgkin lymphomas (NHLs) including the rare lymphoplasmacytic lymphoma, Waldenström's macroglobulinemia (WM)." (PMID 24531446, 2014). "MYD88 mutation is an oncogenic event strongly associated with ABC-DLBCL and Waldenstrom macroglobulinemia, the recurrent L265P mutation of MYD88 accounts for the majority of this association." (PMID 24875472, 2014). "Of importance, oncogenically active MYD88 mutations have recently been identified as recurrent genetic lesions in chronic lymphocytic leukemia (CLL), B-cell lymphoma and Waldenström’s macroglobulinemia." (PMID 23976989, 2013). "No pathogenic mutations associated with Waldenström macroglobulinemia were found in the MYD88 genes." (PMID 38765016, 2024). "MYD88 Leu252Pro (formerly Leu265Pro) mutations are particularly related to lymphoplasmacytic lymphoma/Waldenström macroglobulinemia (LPL/WM), which would not be expected to have a substantial bloodborne component." (PMID 37932435, 2023). "We report a case of mu-HCD with MYD88 L265P mutation along with deletion of 6q, supporting a biologic relationship between mu-HCD and lymphoplasmacytic lymphoma (LPL), a lymphoma that most often presents as Waldenström macroglobulinemia (WM)." (PMID 35932039, 2022).
Waldenström macroglobulinemia (continued). "The prevalence of the somatic MYD88 L265P mutation is over 90% in patients with Waldenstrom macroglobulinemia (WM), and the Bruton tyrosine kinase (BTK) pathway plays an essential role in the signaling of mutated MYD88 providing survival advantage and proapoptotic mechanisms to malignant WM cells." (PMID 36051045, 2022). "Additionally, responses to ibrutinib were influenced by somatic MYD88 and CXCR4 mutations in patients with Waldenström’s macroglobulinemia." (PMID 34368645, 2021). "Although molecular testing for the MYD88 L265P mutation - strongly associated with Waldenström’s macroglobulinemia - was not available in our setting, its detection could further refine the diagnosis and guide the use of targeted therapies." (PMID 41431503, 2025). "No pathogenic mutations related to Waldenstrom macroglobulinemia in the MyD88 and CXCR4 genes." (PMID 38765016, 2024). "Those that expressed MYD88 mutations did not demonstrate differences in median overall survival, time to next therapy from frontline treatment, or median time to progression to active disease in those with smoldering Waldenström macroglobulinemia." (PMID 29712895, 2018). "Notably, the MYD88 L265P mutation, associated with Waldenström's macroglobulinemia, was detected in none of the MM samples." (PMID 27223072, 2016). "The survival of Waldenstrom macroglobulinemia (WM) tumor cells hinges on aberrant B-cell receptor (BCR) and MYD88 signaling." (PMID 27813535, 2016). "Waldenstrom macroglobulinemia (WM) is an indolent yet incurable B-cell lymphoma, in which aberrant B-cell receptor (BCR), Toll-like receptor and MYD88 signaling cooperatively drive tumor cell survival." (PMID 27813535, 2016). "Although MYD88 was negative, the working diagnosis was initially made as isolated Waldenstrom macroglobulinemia (WM), and the patient was treated as such." (PMID 41346800, 2025). "Previous research demonstrated that MYD88 identification in liquid biopsies could aid in monitoring the disease course in patients with DLBCL and Waldenstrom’s macroglobulinemia." (PMID 40507216, 2025). "As such, MYD88 L265P mutation may be the fortuitous finding of other lymphoproliferative disorders -such as IgM monoclonal gammopathy of unknown significance (MGUS), lymphoplasmocytic lymphoma/Waldenstrom macroglobulinemia, or DLBCL-, rather than the rare IVLCBL." (PMID 38441683, 2024).
CNS lymphoma (49 papers, 2012 to 2025). "Gain-of-function mutations in CD79B often coexist with MYD88 mutations in extranodal lymphomas, such as primary central nervous system lymphoma (PCNSL) and primary testicular lymphoma (PTL)." (PMID 40299829, 2025). "Bruton’s tyrosine kinase inhibitors, such as ibrutinib, have demonstrated remarkable CNS penetration and efficacy in primary and secondary CNS lymphomas, particularly in tumors harboring MYD88 mutations." (PMID 41010299, 2025). "cfDNA analysis was proposed as a tool for diagnostics of CNS lymphoma by detecting the L265P MYD88 mutation, which is known to be present in approximately 80% of CNS lymphomas." (PMID 39905397, 2025). "Watanabe and colleagues used a ddPCR approach to demonstrate that MYD88 L265P mutations were detectable in diagnostic CSF samples from 20/26 cases of CNS lymphoma." (PMID 39126310, 2024). "Primary central nervous system lymphoma (PCNSL) are rare mature B-cell lymphoproliferative diseases characterized by a high incidence of MYD88 L265P and CD79B Y196 hotspot mutations." (PMID 38566053, 2024). "The first group, “MYD88” cluster, was defined by MYD88 mutation among others and contained the majority of observed primary CNS lymphomas and primary testicular lymphomas, similarly to MCD and C5 groups." (PMID 36818048, 2023). "We have previously reported a high detection rate of MYD88 L265P mutations in CSF in primary and secondary CNS lymphoma patients using ddPCR, with a 100% match of the MYD88 L265P mutation status between tumor and CSF in 21 cases with available tumor samples." (PMID 33918936, 2021). "This study shows that testing CSF ctDNA for MYD88 mutations is a potentially minimally-invasive approach to diagnosing patients with suspected CNS lymphomas." (PMID 30294590, 2018). "This is consistent with studies showing strikingly high frequencies of MYD88 mutations in primary CNS lymphoma, as well as an increased risk of CNS recurrence in systemic de novo DLBCL patients carrying the MYD88 L265P mutation, particularly in the MCD genetic subtype." (PMID 39853347, 2025). "The detection of the MYD88 L265P mutation strongly suggests the diagnosis of primary CNS lymphoma, and this mutation has been detected in the CSF ctDNA of patients with CNS lymphoma, showing that the analysis of CSF ctDNA could complement the diagnosis." (PMID 33919036, 2021). "We have previously reported a 100% match of the MYD88 mutation status in circulating tumor DNA (ctDNA) extracted from cerebrospinal fluid (CSF) and biopsied tissue in 21 primary and secondary central nervous system lymphoma patients using droplet digital PCR (ddPCR)." (PMID 33918936, 2021). "A pilot study provided evidence that the MYD88 mutation can be reliably detected by a combination of Sanger sequencing and ddPCR in the cell-free DNA (cfDNA) taken from 1 mL of CSF in patients with CNS lymphomas." (PMID 33050534, 2020). "MYD88 mutation has been found in healthy individuals as well as in peripheral blood mononuclear cells of patients with CNS lymphoma, suggesting that this alteration might take place before IGH rearrangement." (PMID 33180881, 2020). "In conjunction, we evaluated the patient-matched CNS lymphoma tissue for MYD88 mutations." (PMID 30294590, 2018). "We present the case of a patient with primary CNS lymphoma (PCNSL), with MYD88 and CD79B gene variants, who was unable to complete standard induction and consolidation treatment due to toxicity and co-morbidities after three cycles of MATRix." (PMID 41226558, 2025). "Multiple studies have demonstrated the utility of ddPCR in detecting canonical recurrent point mutations, specifically MYD88 L265P (present in over 80% of PCNSL tumors) in CSF-derived ctDNA samples from primary and secondary CNS lymphoma patients." (PMID 39126310, 2024). "Nevertheless, MYD88 retains high specificity for CNS lymphomas compared to other brain tumors and infectious or demyelinating diseases." (PMID 40346678, 2025).
CNS lymphoma (continued). "In primary central nervous system lymphoma, the detection of MYD88 L265P in ctDNA offers a highly sensitive, specific, and minimally invasive diagnostic option." (PMID 40430009, 2025). "PCLBCL, LT showed highly recurrent mutations of MYD88 (p.L265P variant), PIM1, and CD79B, which are involved in the NF-κB and B-cell receptor signaling pathways, similar to primary central nervous system lymphoma (PCNSL)." (PMID 35452489, 2022). "The prognostic impact of MYD88 and CD79B mutations vanished if CNS lymphomas were excluded (p = 0.2 and 0.6, respectively)." (PMID 36051079, 2022). "Our cohort lacks genomic data such as mutation status of MYD88 and CD79 which were recently found to be present in IVL as frequently as in primary CNS lymphoma." (PMID 35713565, 2022). "As well, in primary central nervous system lymphoma (PCNSL), mutation MYD88 L265P was identified by ddPCR in cerebrospinal fluid or vitreous fluid with a superior sensitivity when compared with qPCR." (PMID 34205827, 2021). "However, MYD88 L265P alone is insufficient for a definitive diagnosis because it is also found in a large percentage of primary CNS lymphoma cases and, less frequently, in other low-grade B-cell neoplasms, such as CLL or MZL, which rarely involve the CNS." (PMID 41154413, 2025). "Specifically, liquid biopsies detecting MYD88 hotspot variants (p.L265P) have shown promise for the non-invasive diagnosis of CNS lymphoma." (PMID 39115616, 2024). "For primary central nervous system lymphoma (PCNSL), which is a specific extra‐nodal subtype of DLBCL with molecular similarities to MCD type or C5 with frequent mutations in MYD88 and CD79B, SAMD14/neurabin‐I were recently identified by us as an antigen of the BCRs." (PMID 36051037, 2022). "Moreover, MYD88, CD79B, and PIM1 mutations were commonly found in primary CNS lymphomas and DLBCLs with CNS relapse." (PMID 36081566, 2022). "Specifically, the p.L265P amino acid substitution is the most frequent MYD88 mutation in CNS lymphoma." (PMID 34071407, 2021). "The MYD88 p.L265P mutation occurs at high frequency in CNS lymphoma and is extremely rare in non-hematologic malignancies." (PMID 30294590, 2018). "Additionally, identification of MyD88 mutation is highly suggestive of PVRL/CNS lymphoma, although it does not exclude other types of B cell lymphoma." (PMID 35158867, 2022). "Recurrent mutations in the JAK–STAT, NF-κB, and B-cell receptor (BCR) pathways, including CD79B, MYD88, and CDKN2A deletions, have been identified as the defining characteristics of primary central nervous system lymphomas." (PMID 40538656, 2025). "Furthermore, MYD88 mutations are not universally present in CNS lymphomas, and low-level detection in the absence of supportive cytological or radiological findings may be difficult to interpret." (PMID 41226558, 2025). "The MYD88 alteration has been found at high frequencies in cutaneous DLBCL (69%), primary testicular lymphoma (68%), primary central nervous system lymphoma (38–86%), or ABC DLBCL (30%), indicating its role in the pathogenesis of lymphoid neoplasia." (PMID 35628381, 2022). "Remarkably, the MyD88 mutation never occurs in tissue biopsies from nonhematologic brain tumors, such as a glioblastoma, or in solid metastatic tumors, suggesting it is a sensitive and specific biomarker for the differentiation of primary central nervous system lymphoma from other CNS cancers." (PMID 35628381, 2022).